IL6 (interleukin 6)
Diseases named in the same sentence as IL6 in open-access papers (continued):
Sharing a sentence is not in itself a finding about the gene and the disease.
glioblastoma (continued). "IL-6 blockade with a neutralizing antibody transiently sensitizes mouse glioblastoma to anti-PD-1 by increasing MHCII+ monocytes, CD103+ migratory dendritic cells (DCs), CD11b+ conventional DCs, and effector CD8+ T cells, and decreasing immunosuppressive Tregs." (PMID 40161763, 2025). "Low CD90 expression in mesenchymal stromal cells has been linked to increased IL‐6 secretion, EMT induction, and chemoresistance in glioblastoma, as well as contributing to tumor vascularization and immunosuppression due to their higher production of VEGF and PGE2." (PMID 40255916, 2025). "Overall, these findings suggest that quercetin has potential as an anticancer agent for glioblastoma treatment, potentially improving the cancer microenvironment and offering a new therapeutic strategy for managing glioblastoma by targeting the Axl/IL-6/STAT3 signaling pathway." (PMID 41009025, 2025). "Combined IL-6 and PD-1 blockade remodels the tumor microenvironment towards an antitumoral phenotype, albeit transiently, and improves survival in an allograft murine model of glioblastoma whose tumor microenvironment resembles that of the human disease." (PMID 41392975, 2025). "For example, IL-6 has been reported to contribute to immunosuppression in glioblastoma through PD-L1 upregulation in myeloid cells, and higher IL-6 expression has been correlated with worse survival in glioblastoma." (PMID 41392975, 2025). "In addition, the study reported that APOE knockdown in glioblastoma cells attenuated tumor migration/invasion while reprogramming cytokine secretion—elevating antitumor cytokines (IL-6/IL-12/TNF-α) and suppressing immunosuppressive CCL5/TGF-β." (PMID 41390817, 2025). "In our previous studies, we demonstrated that the ethanolic extract of Brazilian green propolis may potentially inhibit tumour progression in grade IV glioblastoma, in part by reducing IL-6 and VEGF concentrations under both hypoxic and normoxic conditions." (PMID 40733274, 2025). "Although these results are encouraging, the changes in the glioblastoma TIME are transient after combined IL-6 and ICI blockade, suggesting that the immunosuppressive TIME is durable and persistent despite treatment and likely necessitating a sustained treatment schedule." (PMID 40161763, 2025). "In addition, studies of glioblastoma have shown that IL-6 expressed by TECs can mediate the alternative activation of macrophages to produce M2-like macrophages with protumor effects." (PMID 39408814, 2024). "Furthermore, it has been shown that BM-MSCs promote senescence of the U87 glioblastoma cell line by inducing changes in cell morphology and by increasing the production of cytokines (IL-6, IL-8, leukemia inhibitory factor (LIF), CCL2/MCP-1, and CXCL2)." (PMID 38607056, 2024). "Indeed, pre-clinical data demonstrated that IL6 blockade combined with CD40 stimulation sensitized glioblastoma to immune checkpoint inhibitors and improved survival." (PMID 37006265, 2023). "Moreover, in the serum of patients with glioblastoma (the most typical parenchymal brain tumor), it has been reported that there is a significant overexpression of IL-6, IL-1β, TNF-α, IL-10, VEGF, FGF-2, IL-8, IL-2, and GM-CSF." (PMID 37368708, 2023). "Finally, in terms of tumor access, IL-6 has been described as the key glioblastoma-derived factor that promotes anti-inflammatory and wound-healing type responses, inducing strategic tissue remodeling to prevent immunologic access to the tumor by T cells." (PMID 38132354, 2023). "Among the cytokines measured, IL-6 emerged as the best marker of inflammation-related glioblastoma." (PMID 38003396, 2023). "Furthermore, BACE1 reduced the phagocytosis of tumor cells in glioblastoma by activating the tumor-promoting macrophages via cleaving interleukin-6 receptor (IL-6R) and activating IL6/sIL-6R/STAT3 signaling." (PMID 38201438, 2023).
glioblastoma (continued). "As CCRK is highly overexpressed in glioblastoma and considered an oncogene, we questioned whether the elevated IL-6 expression and the resulting immunosuppressive phenotype was due to CCRK’s role in cilia morphology versus other unrelated activity." (PMID 38188300, 2023). "IL-6 has emerged as a potential therapeutic target in treatment of glioblastoma." (PMID 38188300, 2023). "In addition, PGK1 T243 phosphorylation correlates with PDPK1 activation, IL-6 expression, and macrophage infiltration in human glioblastoma (GBM) and correlates with the malignancy and prognosis of human GBM." (PMID 37491279, 2023). "Other pathways, such as IL-6, that may enhance the growth and invasion of glioblastoma and also limit T-cell infiltration, are worthy of further research." (PMID 38132354, 2023). "Furthermore EC-derived IL-6 is a cytokine that favors macrophage M2-like polarization, at least in murine glioblastoma." (PMID 36248978, 2022). "IL-6 induces the anti-apoptotic pathways in glioblastoma cells and promotes invasion." (PMID 35954362, 2022). "Cross-signaling between NFkB and IL-6 has been shown in vascular inflammation and glioblastoma." (PMID 35204748, 2022). "The current understanding of tumor-mediated immunosuppression in patients with glioblastoma shows that tumor cells suppress lymphocyte proliferation and interleukin-6 (IL-6) production via secreting prostaglandin E2 (PGE2) and transforming growth factor-β2 (TGF- β2)." (PMID 36299858, 2022). "However, in glioblastoma cells, accumulation of HuR in the cytosol stabilizes the inflammatory cytokine interleukin-6, which contributes to promoting tumor progression and invasion." (PMID 33425493, 2021). "Therefore, we performed an analysis of the mRNA expression of CD109 and the key mediators of the STAT3 signaling pathway (IL6ST/GP130, STAT3, and IL6) in the Human Glioblastoma Cell Culture (HGCC) data set." (PMID 33986188, 2021). "Treatment with anti-IL-6 siltuximab, anti-IL-6R (gp80) tocilizumab or STAT3 inhibitor stattic could abrogate PD-L1 expression and T cell apoptosis, demonstrating the role of IL-6 signalling in regulating T cell responses in glioblastoma through GAMs." (PMID 33803414, 2021). "Additionally, glioblastoma (GBM)-derived IL-6/STAT3 signaling pathway correlated with myeloid PD-L1 expression." (PMID 34088360, 2021). "The finding is supported by published reports that NF-κB induces IL6 expression in glioblastoma." (PMID 33576874, 2021). "For example, in glioblastoma, several proangiogenic molecules are found in TEVs, including angiogenin, fibroblast growth factor, vascular endothelia growth factor, interleukin-6 (IL-6), among others." (PMID 34685415, 2021). "As significant role of IL-6/GP130 in glioblastoma has been recognized long time ago." (PMID 31942189, 2020). "Interestingly, the “guide strand” of miR-142-3p is negatively modulated by interleukin-6 in glioblastoma multiforme (GBM), the most aggressive and stem cell-rich primary brain tumour, causing the upregulation of HMGA2 protein expression." (PMID 31979076, 2020). "In addition, upregulation of the HMGA2/IL-6 axis was shown to be highly correlated with poor outcomes in glioblastoma patients." (PMID 32842685, 2020). "In addition, a blockade of both endogenous and exogenous IL-6 by the treatment with tocilizumab was able to repress autophagy in glioblastoma cells." (PMID 33424586, 2020). "Importantly, PGE2 in glioblastoma cells increases the overexpression of immunosuppressive cytokines, such as interleukin 6 (IL-6), interleukin 10 (IL-10), and granulocyte-macrophage colony-stimulating factor (GM-CSF)." (PMID 32560280, 2020). "And IL-6 was a poor prognostic factor for glioblastoma patients." (PMID 31942189, 2020). "U87 cells express high amounts of IL-6, as do highly aggressive glioblastomas." (PMID 32878114, 2020).
glioblastoma (continued). "Artificially silencing the expression of H2AFJ predominantly repressed the mRNA levels of TNF-alpha and interleukin-6 in D54MG glioblastoma cells, whereas the forced gene expression of ectopic H2AFJ dramatically enhanced the expression of TNF-alpha and interleukin-6 in T98G glioblastoma cells." (PMID 31906036, 2019). "Factors that may transfer from one glioblastoma cell to another and thereby increase the aggressiveness of the recipient cell include Interleukin-6 and Leukemia Inhibitory Factor62,63." (PMID 29445239, 2018). "When these VZV data about IL-6/STAT3/ATG5 are considered together with the results from the glioblastoma/autophagy study, we conclude that the elevated levels of IL-6 may also facilitate elevated levels of autophagy in VZV-infected skin explants." (PMID 30568636, 2018). "Moreover, it has also been reported that the Chip-seq on a Sox2 immuno-precipitate shows a highly efficient binding of Sox2 to the IL6 promoter in glioblastoma or ES cells." (PMID 29337886, 2018). "Interestingly, chromatin immunoprecipitation assays in HT-1080 cells demonstrated that PIBF binds the promoter regions of IL-6, an overexpressed cytokine in glioblastomas that acts as a ligand of the JAK2/STAT3 pathway." (PMID 28168193, 2017). "Importantly, IL-6 derived from cerebral cells, strongly inhibits apoptosis of glioblastoma cell invasion and plays a pivotal role in maintain glioblastoma stem cell properties." (PMID 28891967, 2017). "Taking into consideration that PIBF acts as a transcriptional factor, we suggest a possible role of PIBF in regulating the expression of several target genes such as IL-6 and EGF that could be associated with the invasive effects of glioblastoma cells." (PMID 28168193, 2017). "A number of reports indicated paracrine secretion as paramount to glioblastoma growth, with ligands such as TGFα, IL-6, ΙL-8, HGF and heparin binding EGF playing central role, further supporting the hypothesis." (PMID 27004406, 2016). "Ablation of IL-6 expression in mice genetically predisposed to glioblastomas prevents tumor formation, but not pre-neoplastic astrogliosis, indicating its role in neoplastic progression." (PMID 26291724, 2015). "Previously we found that antibodies raised against the extracellular epitopes of α7 nAChR subunit stimulated pro-inflammatory IL-6 production in cultured U373 glioblastoma cells and were able to decrease the α7 nAChR density in certain brain regions to impair episodic memory of mice." (PMID 25816313, 2015). "Furthermore, the protein level of IL-8 was decreased in all BTICs, and the level of IL-6 was decreased in glioblastoma-BTICs when co-cultured with hAT-MSCs." (PMID 26076490, 2015). "In addition, the quercetin-mediated inhibition of IL-6 decreases proliferative and migratory properties of glioblastoma cells." (PMID 26512639, 2015). "Similarly, invasive/co-optive IRE1α dominant-negative glioblastomas concomitantly exhibited a highly vascularized pattern when producing ectopic interleukin-6." (PMID 26325176, 2015). "IL-6 is a known growth- and survival factor in glioblastomas." (PMID 26291724, 2015). "The present study therefore evaluated the effect of ACA on cytokine expression in glioblastomas, which are known to express IL-6 at high levels compared with normal brain tissue, and have been shown to play a prominent role in glioblastoma cell survival and migration." (PMID 23833677, 2013). "Additionally, IL-6 has been found to enhance the tumorigenicity in glioblastoma, consistent with increased capacity of CSC self-renewal." (PMID 22952749, 2012). "Additionally, IL-6 has been shown to enhance tumorigenicity in glioblastoma, consistent with an increase in the CSC self-renewal capacity." (PMID 23272057, 2012). "Moreover, LLL12 induces apoptosis in medulloblastoma and glioblastoma cells and was also able to inhibit colony formation, wound healing and decreased IL-6 and LIF secretion." (PMID 22530037, 2012).
glioblastoma (continued). "For instance, MSCs can carry the sodium/iodide symporter (NIS) gene, driven by the IL-6 promoter, significantly enhancing glioblastoma (GBM) uptake of radioactive tracers, thereby improving imaging diagnostics and therapeutic outcomes." (PMID 39911388, 2025). "Thus, we hypothesized that the combination of IL-6 and PD-1 blockade could improve survival from glioblastoma." (PMID 40161763, 2025). "Considering the data from preclinical models in the context of data from human glioblastomas before and after treatment with ICI, we hypothesized that IL-6 and the IL-6 signaling cascade may drive glioblastoma tumorigenesis and stemness, and that IL-6 blockade may sensitize glioblastomas to ICI." (PMID 40161763, 2025). "A study on human cytomegalovirus (HCMV)-infected glioblastoma multiforme (GBM) demonstrated that glioma cells overexpressing IE2 exhibited increased expression of IL-6 and IFN-β." (PMID 38542956, 2024). "For example, icaritin inhibits the survival and glycolysis of glioblastoma (GBM) cells through the IL-6/STAT3 pathway." (PMID 38495094, 2024). "The present work aimed at studying the prognostic value of changes in circulating IL-6 levels for glioblastoma by comparing it to other cytokines in GBM patients and healthy controls." (PMID 38003396, 2023). "Besides neuronal IL-6 signaling, BACE1 may also control IL-6 signaling in tumor-promoting macrophages in glioblastoma." (PMID 36810097, 2023). "Guang-Yuh Chiou and his co-workers found that IL6 could induce DNA methyltransferase 1 expression leading to hypermethylation of the miR142-3p promoter which influenced Sp1-binding motif in the promoter to contribution to glioblastoma tumorigenesis." (PMID 35541892, 2022). "Interestingly, IL-6 is strongly expressed by ECs in human and murine glioblastoma tumors." (PMID 36248978, 2022). "Therefore, we can posit that the IL-6 increase observed in our co-culture supernatants of glioblastoma with GD2 CAR T cells might be due to activated CAR T cell release." (PMID 34707200, 2021). "In addition, a strong link between IL-6-STAT3 signaling and O6-methylguanine DNA methyl transferase expression and methylation and to temozolomide sensitivity in glioblastoma was found, suggesting a possible combination therapeutic approach based on IL-6/STAT3 inhibitors." (PMID 31247937, 2019). "Similarly, our study have shown that IL-6 was also elevated in patients with cancer compared to the control group, which support previous studies where IL-6 is expressed in the cytoplasm of glioblastoma, breast, renal, bladder, prostate and cervical cancer cells." (PMID 26148092, 2015). "Moreover, since STAT3 signaling is a downstream effector of interleukin-6 (IL-6), blocking IL-6R alpha or IL-6 expression in GSCs by shRNAs suppresses tumor sphere formation capacity and increases the survival of mice bearing intracranial glioblastoma xenografts." (PMID 24212792, 2011). "The activation of the GPR68-ATF4 signaling pathway can promote the production of the pro-inflammatory factors IL-6 and TNF-α and helps glioblastoma cells to evade immune surveillance, thus enhancing the growth and survival of glioblastoma cells." (PMID 41190345, 2025). "Factors including IL-10, IL-6, VEGF, GM-CSF, PGE-2, and TGF-β2, found upregulated in glioblastoma, also influence MDSCs expansion." (PMID 41208963, 2025). "Exosome-derived IL-6 from human glioblastoma (GBM) cells may trigger autophagy in macrophages by activating the Signal Transducer and Activator of Transcription 3 (STAT3) signaling at least in vitro." (PMID 40191733, 2025). "Corroborating our findings, three key pro-inflammatory cytokines with known anti-tumoural functions (IL-6, CCL5 and CXCL10) are also significantly secreted by ZIKV-infected glioblastoma cells." (PMID 40240536, 2025).
glioblastoma (continued). "Our data further reveals that ICI-resistant human glioblastomas are enriched in genes that induce IL-6, such as LGALS3, and downstream targets of the IL-6 signaling cascade such as p-STAT3, p-AKT, p-ERK1/2, and ANXA113,28,29." (PMID 40161763, 2025). "Together, these results suggest that IL-6 blockade can be combined with ICI and radiotherapy to enhance treatment responses in human glioblastoma patients." (PMID 40161763, 2025). "In human glioblastoma, IL-6 levels are endogenously lower in patients who achieve histological or radiographic responses to ICI, and ICI-resistant glioblastoma has elevated stem cell markers (SOX2, SOX4, SOX13, PTPRZ1), which can be driven by IL-621,58." (PMID 40161763, 2025). "This, in turn, can worsen IL-6-mediated pathological effects through the IL-6/JAK/STAT3 signaling pathway, which is a significant driver of glioblastoma." (PMID 40843259, 2025). "IL‐6/STAT3 signaling, in particular, plays a central role in glioblastoma progression by driving tumor cell survival and creating an immunosuppressive microenvironment." (PMID 41354084, 2025). "To test this, we administered IL-6 and/or PD-1 blocking antibodies systemically to C57BL/6J mice with intracranial SB28 glioblastoma." (PMID 40161763, 2025). "IL-6 derived from glioblastoma induces PD-L1 expression on bone marrow cells via a STAT3-dependent mechanism, therapeutic blockade of IL-6 signaling inhibits tumor growth and improves survival rates." (PMID 38762484, 2024). "Consistently, the MLC proliferation and the expression of IL-6 and IL1R1 were promoted by incubation with conditioned medium from parental glioblastoma cells transfected with siCXCR7." (PMID 38898023, 2024). "However, given the complexity of the tumour microenvironment within glioblastoma and the predominance of immunosuppressive macrophages and microglia, an enhanced inflammatory response especially involving IL-6/JAK/STAT3 pathways may enhance immunosuppression and inadequate T-cell response." (PMID 38227740, 2024). "Examples of such paracrine interactions include glioblastoma, where cancer cells expressing mutant EGFR stimulate the growth of tumor cells with WT EGFR through cytokine secretion (IL‐6 and LIF)." (PMID 37418588, 2024). "QUE has been demonstrated to decrease IL-6 levels in a dose-dependent mode through STAT3 activation in T98G and U87 glioblastoma cells." (PMID 39202863, 2024). "Their data showed that miR-93 was downregulated in human glioblastoma cell lines, and restoration of miR-93 levels in glioblastoma cells led to a decreased expression of an array of inflammatory genes (HIF-1α, MAP3K2, IL-6, G-CSF, IL-8, LIF, and IL-1β)." (PMID 38239396, 2023). "The concentrations of IL-1β, IL-6, IL-8, IL-10, TNFα, and HMGB1 confirmed that inflammation was a critical component of glioblastoma progression." (PMID 38003396, 2023). "Through the release of interleukin-6 (IL-6) and the surface expression of programmed death ligand-1 (PD-L1) and indoleamine 2,3-dioxygenase (IDO) 1, glioblastoma cells induce the recruitment and expansion of Tregs." (PMID 38132354, 2023). "Analysis of the TCGA dataset revealed that IL-6 and IL-6R mRNA levels were significantly higher in mesenchymal subtype and IDH-wildtype glioblastoma." (PMID 38188300, 2023). "IL-6-mediated STAT3 activation enhanced cell migration and invasion in glioblastoma cells (U251, T98G, and U87MG)." (PMID 35368876, 2022). "Analysis of exosomes from glioblastoma cells showed that they are enriched with the proangiogenic factors VEGF, angiogenin, TGFβ, IL-8, IL-6, MMP2, MMP9, TIMP-1, TIMP-2, and CXCR4." (PMID 35740619, 2022). "Ex vivo gas plasmas exposure of patient-derived primary glioblastoma tissue led to significantly decreased release levels of b-NGF, IL-6, sTREM2, TGF-β, TNF-α, and TREM-1." (PMID 35159079, 2022).